TNF (tumor necrosis factor)
Diseases named in the same sentence as TNF in open-access papers (continued):
Sharing a sentence is not in itself a finding about the gene and the disease.
tumor (continued). "Recently, we demonstrated that CAP treated macrophages release tumor necrosis factor (TNF-α), which acts as a tumor suppressor for solid tumors." (PMID 31216715, 2019). "In spite of its name, “tumor necrosis factor”, which would indicate tumor-suppressive activities, there is mounting evidence that TNFα can promote tumor survival and growth through its pro-inflammatory effects." (PMID 31817625, 2019). "In tumor microenvironment (TME), the interaction between PD‐1 expressed on TILs and its ligands PD‐L1 on malignant tumor cells results in decreased cytokine output, including IFN‐γ and TNF‐α, leading to tumor evasion." (PMID 30969023, 2019). "Ovarian cancer cell lines and tumor biopsy specimens express TNF, CCL22, and CXCL12, which induce macrophage polarization into the M2 phenotype in the TME." (PMID 31192126, 2019). "After co-culture with mesenchymal stromal cells (MSCs) primed by TNF-α, neutrophils isolated from bone marrow of normal mice or spleen of tumor-bearing mice acquire immunosuppressive function in vitro and induce tumor progression in vivo." (PMID 31799175, 2019). "TANs are known to secrete multiple growth factors and chemokines such as TNFα, CCL2, IL-8, and IL-17a into the tumor microenvironment, where they promote the growth and invasion of the underlying tumor by triggering multiple pathways." (PMID 30616627, 2019). "One mechanism by which this is thought to occur is due to the heightened production of pro-inflammatory cytokines IFN-γ and tumor necrosis factor-α (TNF-α) from tumor-infiltrating NK cells." (PMID 31163679, 2019). "Its increased expression on tumor cells leads to tumor progression (proliferation) and metastasis, and its expression is dependent on TNFα, IL-1β, IFNγ via toll-like receptors (TLRs)." (PMID 31374832, 2019). "Solanum nigrum treatment decreased the level of blood serum TNF-α, and this corresponds to triggering of apoptosis in tumor cells." (PMID 31731465, 2019). "The tumour necrosis factor α (TNF-α) is one of the important proinflammatory cytokines involved in the tumour microenvironment." (PMID 31565662, 2019). "Mechanistically, STIM1 and STIM2 are crucial for the cytolytic effector functions of CTLs, especially the production of IFN-γ and TNF-α, the release of perforin-containing cytolytic granules, the induction of FasL, and thus tumor cell killing." (PMID 31252656, 2019). "One of the most well-investigated cytokines flooded in the tumor microenvironment is TNF-α, which is capable of embarking on two distinct pathways in deciding life and death of cell." (PMID 30902881, 2019). "In the tumor mass, it is possible to detect an increase in the expression of IL1β, TNFα, and IL10 24 h after its inoculation, whereas IL6 expression increased earlier, just 12 h after cells injection." (PMID 31712726, 2019). "In vitro experiment, researchers found that PARPi-induced apoptosis increased when tumor cells were exposed to additional IFN-γ or TNF-α." (PMID 31521196, 2019). "TNF-α is one of the most well-known mediators of inflammatory stimuli in the tumor microenvironment." (PMID 31921870, 2019). "This peptide binds to laminin–nidogen complexes in the ECM of mouse and human carcinomas with little or no peptide detected in normal tissues, and it selectively delivers a recombinant TNFα‐CSG fusion protein to tumour ECM in tumour‐bearing mice." (PMID 31709774, 2019). "Within the tumor microenvironment, several factors lead to the production of IL-6 and IL-8, including IL-1β and TNFα." (PMID 31781510, 2019). "These EGFR-expressing effector T cells proliferated better and produced more IFN-γ and TNF-α in the presence of EGFR ligands produced by tumor cells in vitro." (PMID 31921216, 2019). "Tumor necrosis factor-α (TNF-α) plays a central role in the regulation of anti-tumor immune responses." (PMID 30509966, 2019).
tumor (continued). "The relationship between mycobacteria and cancer was first recognized almost a century ago, with animal studies demonstrating that BCG-infected mice were resistant to transplantation of tumor cells leading to the discovery of Tumor Necrosis Factor (TNF)." (PMID 31244856, 2019). "In fact, our results show a significant positive correlation between ANGPTL-4 tumor levels and those of IL-1 β, TNF-α, and NFκB, and a tendency toward a positive correlation of MCP-1 tumor levels (p < 0.06) in cancer cachexia patients." (PMID 31741709, 2019). "Once macrometastases are established, multiple factors such as M-CSF, TNF-α, IL-8 and IL-11 released from tumor cells drive osteoclasts to induce osteolytic lesions via the stimulation of RANKL." (PMID 30823602, 2019). "It was also reported that ATLIII inhibits mast cell proliferation, upregulates anti-inflammatory cytokines, and inhibits pro-inflammatory cytokines such as IL-6, IL-8, IL-1β, and TNF-α in tumor microenvironment." (PMID 32038231, 2019). "Taken together, these data suggest that tumor-derived TNF-α activates NF-κB pathway to induce PD-L1 expression on mast cells." (PMID 30808413, 2019). "TNF-α, despite its ability to induce tumour necrosis, is thought to be another proinflammatory cytokine involved in cancer, and there is ample evidence that TNF-α acts as a tumour promoter in several experimental models of cancer." (PMID 31448061, 2019). "In the hypoxic environment, the tumor stroma can increase its secretion of signaling proteins such as tumor necrosis factor-α (TNF-α), TGF-β, PDGF, and hepatocyte growth factor (HGF)." (PMID 31205939, 2019). "Immune cells from 4T1 tumours of mice treated with TNFα‐CSG or CSG were separated by FACS into CD45+/CD11b− and CD45+/CD11b+ cells, and expression of various proteases known to degrade ECM was analysed." (PMID 31709774, 2019). "We target the immune‐modulating cytokine, tumour necrosis factor alpha (TNFα), to tumours using a newly discovered peptide ligand referred to as CSG." (PMID 31709774, 2019). "One argument would be that as much as high TNF levels impede tumor growth, low levels of this cytokine, as observed in tumors, would on the contrary sustain cancer development." (PMID 31417576, 2019). "The immune system environment is characterized by high levels of stimulatory cytokines, such as interleukin (IL)-6, tumor necrosis factor-α (TNF-α), and eotaxin produced by nascent tumor cells and/or by reactive tumor-associated immune cells." (PMID 30814315, 2019). "After Tumor Necrosis Factor (TNF)-ligand binding to the corresponding TNF-receptor expressed on tumor cells, activated T-cells can also indirectly trigger caspase activation and cell death." (PMID 31075880, 2019). "These mutant strains can induce tumor cells to secrete antitumor cytokines, such as IL-1β, IL-18, and TNF-α, thereby suppressing the proliferation of tumor models in mice." (PMID 31598148, 2019). "Stimulation of slanMo with TLR7/8 ligands resulted in a pronounced production of TNF-α, IL-1β, IL-12, and IL-6 allowing for an improved tumor directed cytotoxicity of slanMo and NK cells." (PMID 31191513, 2019). "TNFα‐CSG treatment also reduced other tumour ECM components, which included fibrillar collagens (stained with picrosirius red), collagen I, perlecan (HSPG2) and fibronectin (Fig EV4B)." (PMID 31709774, 2019). "Despite their high basal motility, the interactions of MDA-MB-231 cells with MSCs in the presence of TNFα have led to significantly higher migratory capacity of the tumor cells compared to tumor cells grown alone (Figure 9A2)." (PMID 31031757, 2019). "We demonstrated that TAMs are the major source of CCL8, and CCL8 and SIGLEC1 engage in a tumor cell-TAM regulatory loop, involving TNF-α, which in turn enhances their expression and leads to increased tumor cell motility." (PMID 30930117, 2019).
tumor (continued). "Significant correlations were found between the levels of PD-L1+ mast cells and pro-inflammatory cytokine TNF-α in GC tumors, and tumor-derived TNF-α activated NF-κB signaling pathway to induce mast cell expression of PD-L1." (PMID 30808413, 2019). "To evaluate the effects of TNFα‐CSG on tumours, we focused on the RIP1‐Tag5 and 4T1 models because these tumours have different levels of immune infiltrates but share abundant ECM and thus CSG targets." (PMID 31709774, 2019). "The initial experiments were carried out using Meth A and L929 mouse tumor lines, which are highly sensitive to TNF-induced cell death." (PMID 31457011, 2019). "In this work, we present a cellular model to understand the role of TNF-α in a tumor MDR microenvironment." (PMID 31137684, 2019). "TNFα can either destroy tumor vasculature and induce apoptosis as an antitumor effector or stimulate the expression of angiogenic and growth factors to promote tumor formation and growth." (PMID 32117199, 2019). "Mast cells influence the primary tumor mainly by the production of many pro-angiogenic factors, such as VEGF, bFGF, TGF, TNF-α, tryptase, heparin and various MMPs, which are associated with ECM degradation, angiogenesis, progression and growth of OSCC." (PMID 30927923, 2019). "Below, we direct the reader to several studies that highlighted the role of lysophosphatidic acid (LPA), extracellular matrix (ECM) fragments, interleukin 6 (IL-6), and tumor necrosis factor alpha (TNFα), in the regulation of detached tumor survival." (PMID 31817625, 2019). "TNFα is often an essential tumour promoter through mediating the production of pro-inflammatory factors." (PMID 30875877, 2019). "The contacts between the tumor cells and the MSCs set the stage for the activities of TNFα which increased CXCL8 production, in a process that was entirely dependent on p65 activation (Figure 3B2)." (PMID 31105691, 2019). "It induces mouse DC maturation and stimulates IL-1β, TNF-α, IL-12p70 secretion in DCs, and enhances T cell infiltration and Th1 polarization in Lewis-bearing tumor tissues." (PMID 31719837, 2019). "In vitro experiments showed that these cells display a strongly reduced capacity to kill PD-L+ tumor cells as well as impaired release of interferon-γ (IFN-γ) and tumor necrosis factor-α (TNF-α) cytokines after stimulation with the same PD-L+ tumor targets." (PMID 30791364, 2019). "We have constructed a recombinant TNFα fusion protein that specifically localises to tumour laminin–nidogen complexes when injected systemically into mice bearing desmoplastic tumours." (PMID 31709774, 2019). "Notable downregulation of growth factors (VEGFD, FGF2, PGF, TNF-α) and cytokine IL-1A was observed in tumor cells upon treatment with 5a." (PMID 31842391, 2019). "It has been reported, that TNF-α as an activator and modulator of tumorigenesis induces the invasion abilities of tumor cells, but very little data is available regarding the impacts of TNF-β/TNF-βR on promoting tumor cell migration and EMT." (PMID 30917533, 2019). "After treatment with COS, significantly elevated concentrations of Bax and reduced expression of Bcl-2 in tumor tissues, as well as elevated levels of TNF-α, IL-2, Fas and Fas-L in mice serum were observed (p < 0.05)." (PMID 30791594, 2019). "The fraction of CD8+ T cells (IL-2+, TNFα+ or IFN-γ+) decreased in CD8+ T cells from 4T1-bearing mouse spleens compared with CD8+ T cells from spleens of tumour-naive mice." (PMID 31594465, 2019). "M1 macrophages are induced by bacterial products such as lipopolysaccharide (LPS), tumor necrosis factor (TNF), and interferon (IFN)-γ secreted by Th1 cells, and can phagocytose directly and kill pathogenic microorganism and tumor cells." (PMID 31572403, 2019). "In the case of immunosuppressive cytokines, we describe strategies to block the activity of tumour necrosis factor-alpha (TNF-α), TGF-β and cytokines that nurture tumour-associated myeloid cells, such as colony-stimulating factor-1 (CSF-1)." (PMID 30413827, 2019).
tumor (continued). "Subsequent efforts to use TNF as an anti-tumor agent in patients largely failed, due in part to the fact that TNF administration induces an intolerable systemic inflammatory response." (PMID 31457011, 2019). "TNFα‐CSG treatment resulted in a more homogenous distribution of tumour stiffness, with significantly reduced stiffness variability in the range well below 100 kPa." (PMID 31709774, 2019). "This interaction between cytotoxic T-cells, TNF, and MDSCs has been verified in in vivo studies in which the expression of exogenous TNF was abrogated in mouse tumor models using an adenoviral vector." (PMID 31182960, 2019). "It is possible that the release of type I IFN, together with TNFα, has a direct effect on the tumor vasculature and the killing of tumor cells." (PMID 31511510, 2019). "Subsequently, the infiltrating macrophages promoted the residual tumor cells to produce CCL2 through TNFα." (PMID 31780645, 2019). "Combined use of ANF and anti-PD-L1 antibody significantly increased infiltration of CD8+, CD4+, and CD3+ T lymphocytes into tumor tissues, and upregulated the expression of IFNγ and TNFα." (PMID 30850589, 2019). "To simulate the activation of the pathway by cells of the tumor microenvironment, we treated all cell lines with 40 ng/mL of TNF-α (a known factor for activating the NFκB pathway 54) for 40 min." (PMID 31602271, 2019). "Direct exposure of cultured 4T1 and RIP1‐Tag5 tumour cells to TNFα‐CSG, even at concentrations sevenfold to 18‐fold higher than estimated in vivo levels, did not significantly reduce cell viability." (PMID 31709774, 2019). "The recruited neutrophils present high expression of tumor-promoting genes such as TNF-α, CXCL1, MMP9, and VEGF." (PMID 31474975, 2019). "T cells reduce the viability of tumor cells via secretion of the cytokine TNF-α, but the overexpression of D2-like receptor genes down-regulates this effect." (PMID 31850367, 2019). "In H22-generated hepatoma-bearing mice, PD-L1 is upregulated in tumor-infiltrating neutrophils (TINs), induced by GM-CSF and TNF-α secretion from the tumor microenvironment." (PMID 31474975, 2019). "TNF-α is involved in almost all carcinogenesis stages and performs various functions depending on the tumor type and TME." (PMID 31861801, 2019). "Paradoxically, these cells can inhibit TNFα and IFNγ which are initially necessary for licensing or “tumor-mediated education,” while also increasing IL-10, an immunosuppressive cytokine." (PMID 31788448, 2019). "The results showed that the combined ginkgetin–resveratrol treatment significantly reduced the levels of TNF-α and IL-6 cytokines in 5-FU-treated tumor tissues, which were consistent with the expression of COX-2 protein." (PMID 31757048, 2019). "Tumor cell-derived mediators such as TNFα, IL-6, TWEAK, myostatin and extracellular vesicle HSPs have been postulated to play a role in the pathogenesis of cancer cachexia." (PMID 31851697, 2019). "Another group showed that pro-inflammatory cytokines TNFα, IL-6, CSF-1, and IFNγ correlated with disseminated tumor cells in BC18." (PMID 30814616, 2019). "On the other hand they produce less GMCSF and TNFα, cytokines important in establishing an anti-tumour response." (PMID 30872676, 2019). "They inhibit tumor progression by releasing cytokines such as interferon-γ and tumor necrosis factor-α." (PMID 31817109, 2019). "Another explanation for why TNF failed as an anti-tumor agent is that TNF is a poor inducer of tumor cell death when used as a single agent, contrary to its initial description as a cytotoxic factor." (PMID 31457011, 2019). "It was initially believed that TNF mediated anti-tumor effects via direct cytotoxic or cytostatic actions on malignant cells." (PMID 31174326, 2019). "In tumor microenvironments, changes in TNF-α mRNA expression and Type I TNF receptor signaling modulate MDM differentiation to favor the M2 phenotype." (PMID 31027182, 2019).
tumor (continued). "Using the Gan mouse model, we identified NADPH oxidase organizer 1 (Noxo1) as a TNF-α-dependent tumor-promoting factor for gastric tumorigenesis." (PMID 30700829, 2019). "TAM cells secrete epidermal growth factor (EGF) and TNF-α, while tumor cells secrete colony-stimulating factor-1 (CSF-1)." (PMID 31192126, 2019). "Based on our findings at the mRNA levels, it is possible that DLL1, whose expression was elevated in MSCs by TNFα and IL-1β stimulation (through a p65-mediated pathway, as analyzed for TNFα stimulation), is a partner of tumor cell-expressed Notch1." (PMID 31105691, 2019). "In previous studies, patients with stage III and IV tumours expressed more TNF-α; in the researchers’ country, patients with advanced disease stage are patients with a low level of education." (PMID 31870104, 2019). "Among tumor microenvironment, endothelial cells are converted to fibroblast-like cells in the presence of TNF-α." (PMID 31398937, 2019). "More importantly, the adoptive transfer of TNF-α-treated Th9 cells induced more potent antitumor effects than regular Th9 cells in mouse tumor model." (PMID 30717817, 2019). "CD4+ T cells can also become directly cytolytic to tumor cells, for example via tumor necrosis factor (TNF)-related apoptosis-inducing ligand (TRAIL) or Fas/Fas ligand (FasL) pathways." (PMID 30956760, 2019). "Next, we found that the concentrations of TNF-α in tumor tissues or TTSC were significantly increased when compared to that in non-tumor tissues or NTCS." (PMID 30808413, 2019). "TNF-α can kill or inhibit tumor cells, enhance the phagocytosis of neutrophils, and induce the synthesis of proteins in the acute phase of hepatocytes." (PMID 31344969, 2019). "In another study, the same treatment combination showed a higher elevation of CD4+ and CD8+ T cells and IL-12, IFN-y and TNFα together with a delay in tumour growth and improved survival in mice treated with the combination therapy." (PMID 31111237, 2019). "In the context of TNFR1 signaling, priming of tumor cells with TWEAK enhances TNF-induced caspase-8 activation and apoptosis." (PMID 31885495, 2019). "In vivo, mice repeatedly treated with infliximab or etanercept (biological treatment anti-TNFα) showed different effects, including a reduction in tumor growth and in liver metastases." (PMID 30764482, 2019). "To confirm the involvement of T cells in anti‐tumour immunity, we treated immunodeficient 4T1 tumour‐bearing BALB/c nude mice with TNFα‐CSG in the absence or presence of adoptively transferred naive splenic T cells." (PMID 31709774, 2019). "The first observation directly linking TNF to tumor promotion came from Prof. F. Balkwill's laboratory." (PMID 31417576, 2019). "At high concentrations, TNF-α correlates with tumor regression, and at long-term low concentrations, it contributes to tumor progression by stimulating the expression of other growth factors and cytokines." (PMID 31861801, 2019). "TNF-α, which was flooded in the tumor environment, has been adapted into a pro-survival inflammatory factor promoting lymphangiogenesis regulated by RIP1 in GBC." (PMID 30902881, 2019). "As TNFRSF1B is more highly expressed than TNFR1 in tumors and tumor-related cells, TNF is likely to have a tumor-promoting function instead of an inhibitory impact." (PMID 32039005, 2019). "The role of TNF-α signaling in tumor progression was demonstrated by comparing the growth of B16-F1 murine melanoma xenograft in wild-type (WT) mice and mice with germline deletions of both TNF-α receptors (TNFR 1 and 2)." (PMID 31656195, 2019). "In some tumor types, TNF-α was shown to promote tumor cell migration and metastasis by inducing RAS or c-MYC activation and expression of MMPs (e.g. MMP-3 and 9)." (PMID 31600735, 2019). "As a further hallmark of T-cell activation upon tumor lysis, a number of cytokines were released into culture supernatants, including IFN-γ, TNF, IL-6, and IL-2." (PMID 31293575, 2019).